CRP (C-reactive protein)
Diseases named in the same sentence as CRP in open-access papers (continued):
Sharing a sentence is not in itself a finding about the gene and the disease.
parasitemia (continued). "The C-reactive protein (CRP) levels increase transiently on the third day after infection (19–20 mg/mL, normal up to 15 mg/mL); but, the increase is significant on day 13 and it peaks on day 15 (161 mg/mL), concomitant with the onset of peripheral parasitemia." (PMID 35327136, 2022). "In addition, PCT was correlated with parasitemia and had better specificity at indicating severe falciparum malaria than CRP." (PMID 36141662, 2022). "There were also no significant changes in platelet reactivity to the different stimuli with the exception of a marked reduction in P-selectin and fibrinogen binding response to low concentrations of CRP-XL at the peak of asexual parasitemia and during gametocytemia." (PMID 35839244, 2022). "The most archaic physiological roles of CRP seem to be detoxication of heavy metals and other chemicals followed or accompanied by an acute phase response and host defense against bacterial, viral as well as parasitic infection." (PMID 35402541, 2022). "Of note, the perturbation of the liver damage parameters ALT, AST, total bilirubin, and also MDP values of IL-4, IL-6, IL-8, IL-12p70, CXCL9, CCL5, CCL2, CRP, fibrinogen and parasitemia levels showed an inverse correlation with the time living in the endemic area." (PMID 34727121, 2021). "However, for future analyses on CRP, parasitemia should be also considered and treated as a confounding variable." (PMID 34565334, 2021). "Also, increasing IL-6 levels mediates the production of acute-phase reactant proteins such as C-reactive proteins (CRP) and secretory phospholipase A2 (sPLA2) whereas moderate levels can reduce parasitemia." (PMID 33281757, 2020). "Setting out for about 500 million years of evolution the most archaic physiological roles of CRP seemed to be detoxication of heavy metals and other chemicals followed or accompanied by an acute phase response and host defense against bacterial, viral as well as parasitic infection." (PMID 35402541, 2022). "The parameters with statistically significant positive correlations with the total parasitemia percentage were WBC, RDW, PDW, %LYM and CRP." (PMID 34565334, 2021). "Moreover, considering the parameters that are correlated with the total percentage of parasitemia such as WBC, PLT, and CRP, it might be possible to assess the level of parasitemia in combination with the WBC histogram analysis, especially in P. vivax infections." (PMID 34565334, 2021). "Parameters like CRP (rs = 0.325, p < 0.001), WBC (rs = 0.285, p < 0.001) and PLT (rs = − 0.303, p < 0.001) were correlated with the parasitemia of P. vivax samples." (PMID 34565334, 2021). "Inflammation (CRP > 5 mg/L and/or AGP >1 g/L) was found in more than one third of the children (39.5%) and parasite infection in 18% of the children." (PMID 26751473, 2016). "A statistically significant higher CRP concentration (U = 478.00, Z = −5.75, P < 0.001), a higher HES (U = 879.00, Z = −7.73, P < 0.001), and higher levels of parasitemia (U = 252.00, Z = -8.00, P < 0.001) were observed in seronegative dogs compared with seropositive dogs." (PMID 40817086, 2025). "It would be worth exploring whether other inflammatory markers could be more related to parasitemia and could be used to adjust ferritin for inflammation, in addition to AGP and CRP." (PMID 39450524, 2024). "In this case, the CRP was as high as 26.55 mg/L before death, and the PCT was within the normal range, which could exclude the possibility of bacterial, fungal and parasitic infections." (PMID 37667198, 2023). "Additionally, it has been reported that parasitic infection is accompanied by joint pain and elevated levels of ESR and CRP." (PMID 35492365, 2022). "Both the IMS and CRP are influenced by presence of malaria parasitemia, though the large drop in specificity observed in CRP between patients with- and without malaria parasitemia suggests that the effect of parasitemia is stronger on CRP." (PMID 33647009, 2021).
parasitemia (continued). "Interestingly, maternal parasitic infections did not influence maternal or neonatal CRP values either." (PMID 38937587, 2024). "This study measured C-reactive protein, IL-4, and TNF-α levels to determine the inflammatory status of patients who showed elevated levels of C-reactive protein and TNF-α in diabetic patients with or without parasite infections." (PMID 39199338, 2024).
Hyperinsulinemia (46 papers, 2005 to 2025). An increased concentration of insulin in the blood. "There is a significant correlation at the baseline between CRP and insulin response, and high levels of CRP are associated with hyperinsulinemia." (PMID 28404960, 2017). "Elevated CRP levels are observed in many systemic diseases, including PCOS pathogenesis, which is associated with low-grade chronic inflammation and hyperinsulinemia." (PMID 39768981, 2024). "The inflammatory marker C-reactive protein (r = 0.29) as well as the hyperinsulinemia marker C-peptide (r = 0.28) were also correlated with FABP-4." (PMID 37833736, 2023). "The present study included prepubertal girls and boys with and without MetS in whom we assessed two bone turnover markers, i-P1NP and CTX-1, and their relationships with MetS and factors associated with MetS (CRP, HOMA-IR, fasting hyperinsulinemia)." (PMID 35334861, 2022). "Our study population displayed at least one characteristic of metabolic dysfunction (i.e., either hyperinsulinemia or glucose levels in the range of impaired fasting glucose or abnormal CRP levels) and are either overweight or obese." (PMID 32486256, 2020). "siMS score correlated with associated factors of MS: hyperinsulinemia and IR, ALT, gama-GT, FLI, uric acid in both groups and CRP (p < 0.01) in group I. Correlations in II group: siMS score with PAI-1 (p = 0.01), microalbuminuria (p = 0.006), homocysteine ​​(p = 0.076)." (PMID 36685849, 2022). "In particular, unlike T1D patients, recent-onset T2D patients showed hyperinsulinemia, and increased high-sensitivity CRP, indicating a possible mechanism for hyperinsulinemia-induced systemic inflammation in the pathogenesis of premature baroreceptor dysfunction." (PMID 33260799, 2020). "Baseline CRP levels were positively correlated (r = 0.3513, p < 0.05) with baseline fasting insulin levels, indicating a close relationship between systemic inflammation and hyperinsulinemia." (PMID 32486256, 2020). "Given that hyperinsulinemia may exacerbate health conditions and inflammatory processes in women with PCOS, metformin has been shown to reverse elevated IL-8 levels in PCOS women[i] and is associated with marked reduction in serum CRP." (PMID 40179096, 2025). "We previously developed and validated an empirical hypothesis-driven food-based dietary index for hyperinsulinemia and inflammation that were based on habitual diets and strongly predictive of C-peptide and inflammatory markers CRP, IL-6, and TNF-α receptor-2 concentrations." (PMID 36943385, 2023). "siMSscore correlated with associated factors of MS: hyperinsulinemia and IR (insulin, mean insulin value, HOMA-IR), ALT, GGT, FLI, uric acid (p < 0.01) in both groups as well as with CRP (p < 0.01) in group I, p = 0.005 in group II, log CRP (p < 0.01) in group I and p = 0.003 in group II." (PMID 36685849, 2022). "Several human studies show elevated CRP levels correlate with the development of T2DM, even without adjustment of other parameters, such as adiposity, hyperinsulinemia, hypertriglyceridemia, and low HDL cholesterol." (PMID 35620114, 2022).
Splenomegaly (46 papers, 2009 to 2026). Abnormal increased size of the spleen. "This may justify its use even in low-risk patients harboring one of the risk factors based on CRP and albumin, especially if splenomegaly is already present." (PMID 36900271, 2023). "The data revealed a significant positive correlation between splenomegaly and the inflammatory markers such as CRP, IL‐6 and ferritin, reinforcing the strong link between splenic involvement and inflammation." (PMID 40637365, 2025). "Duration of fever >4 days, rising trend of fever, coated tongue, splenomegaly, C-reactive protein (CRP) (>25 mg/L), serum glutamic pyruvic transaminase (SGPT) (>40 IU/L), and absolute eosinopenia were independent predictors of EF in this study." (PMID 40497217, 2025). "The potential factors considered in the analysis included gender, age, fever, CRP subgroups (<6.23 and ≥6.23), splenomegaly, administration of antibiotics, presence of anti-HLA-I antibodies, number of pregnancies, and the type of hematologic disease." (PMID 39731480, 2025). "The JAK2 inhibitor ruxolitinib controls not only constitutional symptoms and splenomegaly, but also lowers CRP levels and increases albumin concentration." (PMID 36900271, 2023). "ESR was within normal limits in all patients (mean 11 mm/H, SD 6); CRP was normal (1.37 mg/l, SD 0.61) in all patients with the exception of one (8.81 mg/l) who also had splenomegaly and abdominal pain." (PMID 30562400, 2018). "we built the CRP-A nomogram model based on serum CRP level (>26.8 mg/L), age > 60 years, hepatomegaly and/or splenomegaly, HGB ≤80 g/L, and PC type, which demonstrated robust discriminative performance in stratifying the 1-year, 3-year, and 5-year survival of iMCD patients." (PMID 40309739, 2025). "On univariate analysis, a CRP level of ≥0.30 mg/dL (hazard ratio (HR) 3.620, 95% CI 1.098–11.980, P=0.035), CKD presence (HR 3.332, 95% CI 1.113–9.974, P=0.031), and splenomegaly (HR 3.680, 95% CI 1.234–10.970, P=0.019) were extracted as risk factors." (PMID 38362014, 2024).
liver cancer (45 papers, 2012 to 2026). An epithelial or non-epithelial malignant neoplasm that arises from the liver. "Elevated YKL-40 was strongly associated with increased risk of liver cancer and, to a lesser degree, bladder cancer, clearly outperforming CRP for these cancers." (PMID 40188292, 2025). "At the same time, CRP, another significant indicator of inflammation dependent on IL-6 expression, is associated with inflammatory liver damage and liver cancer progression." (PMID 38166634, 2024). "We aimed to evaluate the effect of MetS combined with high hs-CRP levels on the risk of primary liver cancer (PLC)." (PMID 35927639, 2022). "Elevated CRP concentrations at baseline have been associated with subsequent liver cancer incidence and mortality in chronic liver disease." (PMID 35223421, 2021). "In a recent cohort analysis in China, higher serum CRP levels at baseline were associated with liver cancer incidence and death from CLD." (PMID 26927700, 2016). "Nevertheless, liver cancer is also associated with inflammation and exhibited similar CRP levels to, and higher leukocyte levels than, echinococcosis." (PMID 22340429, 2012). "Therefore, elevated levels of these inflammatory markers (i.e. IL-1β, IL-4, IL-6, IL-10, TNF-α and C-reactive protein) increase the risk of liver cancer development." (PMID 37990536, 2023). "To this end, in the current study, we applied two-sample MR methods to assess the genetic associations of ten extrahepatic immune-mediated diseases, seven circulating inflammatory biomarkers (e.g., CRP and leukocyte count), and 228 blood inflammatory cytokines with the risk of liver cancer." (PMID 37296892, 2023). "In addition, one prospective study, based on the Linxian Nutrition Intervention Trials cohort, recently showed that the C-reactive protein (CRP) concentrations positively increased the risk of both liver cancer incidence and CLD mortality." (PMID 35047538, 2021). "Competing risk method has not been used in a large-scale prospective study to investigate whether increased levels of high-sensitivity C-reactive protein (hs-CRP) elevate the risk of primary liver cancer (PLC)." (PMID 33256656, 2020). "Similarly, another nested case-control study in 2015 found a significant association between higher serum CRP and elevated risk of liver cancer incidence as well as chronic liver disease mortality." (PMID 33256656, 2020). "It appears that high levels of CRP might be related to the increased risk of liver cancer incidence." (PMID 32076459, 2020). "However, the association between CRP and liver cancer incidence was only seen in the males." (PMID 33256656, 2020). "In human liver cancer HepG2 cells, it was discovered that UA enhances the expression of CRP in a dose-dependent manner." (PMID 38977840, 2024). "Studies have shown that C-reactive protein and IL-6 levels are significantly positively correlated with the severity of inflammation, and IL-6 induces C-reactive protein expression in liver cancer cells." (PMID 38769368, 2024). "Here, a systematic review and meta-analysis was performed to evaluate the significance of the combined use of AFP and CRP values in predicting the clinical outcomes of liver cancer patients treated with immunotherapy." (PMID 36915049, 2023). "Numbers and percentages of immune cells, concentrations of CRP and liver cancer biomarkers (AFP, CEA and CA19-9) were detected in the blood of the two groups of patients." (PMID 36290905, 2022). "Oncologists are aware that CRP and IL-6 values can be elevated in liver cancer." (PMID 40419900, 2025). "C-reactive protein (CRP) is an acute-phase reactant protein synthesized by hepatocytes in response to inflammatory cytokines and is thought to be an important prognostic marker of liver cancer." (PMID 36915049, 2023). "This study identified C-reactive protein, IL-6, C-peptide, and non-high weight adiponectin as risk factors for liver cancer." (PMID 28894136, 2017).
liver cancer (continued). "Inflammatory markers such as C-reactive protein (CRP) and interleukin-6 (IL-6) are often elevated in liver cancer, making it difficult to monitor for bacterial infection." (PMID 40419900, 2025). "This suggests distinct prognostic roles for YKL-40 and CRP, and highlights YKL-40 as a promising biomarker for liver cancer." (PMID 40188292, 2025). "Binary Logistics regression analysis indicated that ECV, CRP, IL-6, and NEU were factors influencing the efficacy of ICIs in liver cancer patients (P < 0.05)." (PMID 41199834, 2025). "The intrahepatic tumor number, macrovascular invasion, Barcelona Clinic Liver Cancer (BCLC) stage, NLR, CRP level, and prior ATB were identified as significant predictors associated with the PFS based on mRECIST." (PMID 36749777, 2023). "For instance, the significant dose‐dependent reduction of CRP in the liver suggests the hepatoprotective ability of DHM against a marker proposed for liver damage and increased risks of liver cancer." (PMID 32267550, 2020). "In chronic liver disease and primary liver cancer, IDA frequently co-occurs with systemic inflammation and malnutrition, and biomarkers such as albumin, C-reactive protein, neutrophil–lymphocyte ratio, and platelet–lymphocyte ratio are prognostic in both liver cancer and GC." (PMID 41464174, 2025). "Within the CUP or CRP group, it was crucial to further compare biomarkers and combination panels between the MLC and PLC groups to explore if the therapeutic efficiency of TrxR and other TMs were affected by the type of liver cancer." (PMID 33727662, 2021). "Although there were several studies concerning the relationship between the prognosis of HCC and CRP, no study analyzed the relationship between CRP and liver cancer grading or micro-vascular infiltration." (PMID 30254101, 2018). "The predictive effect of CRP on 30-day CSI was not affected by preoperative infection, liver cancer, organ failure number, and MELD score quartiles." (PMID 34439862, 2021). "In our study, both CRP-activated and non-activated platelets as well as activated platelet releasate strongly increased HCC cell proliferation, indicating that platelets play an important role in liver cancer growth." (PMID 28638139, 2017).
syphilis (45 papers, 2009 to 2025). A contagious bacterial infection caused by the spirochete Treponema pallidum. "Preliminary investigations included bloods (full blood count, liver profile, CRP, albumin), and syphilis serology." (PMID 39394298, 2024). "Preliminary investigations included full blood count, haematinics, renal and liver profiles, glucose, C-reactive protein (CRP), serum angiotensin-converting enzyme, anti-tissue transglutaminase (tTG) and syphilis serology." (PMID 39394298, 2024). "Preliminary investigations included a full blood count, haematinics, renal and liver profiles, CRP, HbA1c, connective tissue disease screen, immunoglobulin levels, syphilis serology and viral swabs of the ulceration." (PMID 39394298, 2024). "Other blood analyses for testing liver and kidney function, C-reactive protein, anti-nuclear antibodies, thyroid function, syphilis serology, and HIV were all within the normal ranges." (PMID 37056784, 2023). "Among these individuals, 41 (8%) were excluded from analysis due to being positive for HIV (6, 14.6%), HBsAg (12, 29.2%), Syphilis (2, 4.9%) and positive for CRP (23, 56.1%)." (PMID 33591978, 2021). "The chest X-ray accounted for 56% of the overall cost for this step, the complete blood count for 22%, the syphilis serology for 12%, and the C-reactive protein/erythrocyte sedimentation rate for 10%." (PMID 32059021, 2020). "Results of systemic examination by the internist, complete blood cell count, sedimentation rate, C-reactive protein, syphilis serology, skin tuberculin test, chest X-ray, and oculo-cerebral magnetic resonance imaging were unremarkable." (PMID 26335662, 2015). "Serum studies demonstrated normal antinuclear antibodies (ANA), thiamine, anti-Ro, anti-La, thyroid stimulating hormone (TSH), free T3/free T4 (fT3/T4), thyroid peroxidase (TPO) and thyroglobulin (TG) antibodies, syphilis screen, borrelia IgG/IgM antibodies, C-reactive protein (CRP)." (PMID 39628892, 2024). "Whole blood samples can easily be collected from all people with syphilis, and the higher sensitivity of PCR positivity in participants with elevated CRP levels suggests an efficient molecular epidemiological analysis by selectively choosing patients for whole blood samples." (PMID 39415268, 2024). "Other lab tests were ordered including complete blood count, complete metabolic panel, erythrocyte sedimentation rate, C-reactive protein, syphilis serology, HSV and VZV titer, human immunodeficiency virus (HIV) antibodies, chest X-ray, and MRI of the brain and orbit with and without contrast." (PMID 26069511, 2015). "Selected patients then have the following bloods sent; urea and electrolytes, full blood count, liver profile, bone profile, C-reactive protein, ESR, Angiotensin converting enzyme and syphilis serology." (PMID 34326494, 2022). "Laboratory investigations, including complete blood count, erythrocyte sedimentation rate, C-reactive protein (CRP) levels, serum antibodies of mycobacterium tuberculosis, syphilis and HIV and tumor-related markers, were all within the normal range, except for a slight increase in CRP (10.1 mg/L)." (PMID 40235656, 2025). "Additionally, they suggest early laboratory assessment including CBC, ESR, CRP, ANA, anticardiolipin antibodies, lupus anticoagulant, anti-neutrophil cytoplasmic antibodies, clotting factors, and syphilis serology." (PMID 33968458, 2021). "Results of chest X-ray, blood cell count, C reactive protein, PPD, and syphilis serology were normal or negative." (PMID 28536985, 2017). "In addition, blood tests for C reactive protein; antinuclear, anticardiolipin and antiendomysial antibodies; and HIV and syphilis serology were all normal or negative." (PMID 33310885, 2020).